SCN1A (sodium voltage-gated channel alpha subunit 1)
Diseases named in the same sentence as SCN1A in open-access papers (continued):
Sharing a sentence is not in itself a finding about the gene and the disease.
Dravet syndrome (continued). "Dravet syndrome is most frequently caused by various mutations of the SCN1A gene encoding the type 1 subunit of the neuronal voltage-gated sodium channel." (PMID 27021235, 2016). "Mutations in SCN1A, encoding Nav1.1, result in a broad spectrum of disorders ranging from simple febrile seizures to Dravet syndrome, a severe, infant-onset epileptic encephalopathy with devastating outcomes." (PMID 27768696, 2016). "Heterozygous loss-of-function mutations in the SCN1A gene are the most common genetic basis for Dravet Syndrome." (PMID 27458797, 2016). "Dravet Syndrome is an intractable form of childhood epilepsy associated with deleterious mutations in SCN1A, the gene encoding neuronal sodium channel Nav1.1." (PMID 27458797, 2016). "SCN1A mutations result in a spectrum of severity ranging from mild febrile seizures to Dravet syndrome, an infant-onset epileptic encephalopathy." (PMID 27768696, 2016). "A loss of function mutation of SCN1A has been linked to an epilepsy disorder called Dravet Syndrome (DS)." (PMID 26542295, 2015). "The discovery in 2001 that de novo mutations in SCN1A cause Dravet syndrome, one of the best-studied EEs, set the stage for the de novo paradigm for this class of disorders." (PMID 26302787, 2015). "Although the incidence of Dravet Syndrome was somewhat higher than others have found, the percentage of Dravet patients with a SCN1A mutation (75%) is similar to previous reports." (PMID 26933548, 2015). "Mutation in SCN1A, a gene encoding voltage-gated sodium channel, has been demonstrated to be involved in Dravet syndrome." (PMID 25874049, 2015). "Mutations in a voltage-gated sodium channel (SCN1A) result in Dravet Syndrome (DS), a catastrophic childhood epilepsy." (PMID 26465006, 2015). "By contrast, sodium channel blockers usually exacerbate seizures in patients with Dravet syndrome, which is caused by a deficiency of SCN1A activity." (PMID 26029160, 2015). "About 80% of patients with Dravet syndrome, for example, carry a de novo mutation in the gene SCN1A." (PMID 26613940, 2015). "SCN1A and SCN2A are associated with a variety of epilepsy syndromes; most notably, Dravet syndrome is caused by an SCN1A mutation in over 80% of reported cases." (PMID 26933559, 2015). "Patients with an SCN1A mutation accounted for the largest proportion, 17% (8/46), of which seven patients were diagnosed as Dravet syndrome and one patient was diagnosed as MMPSI." (PMID 26544041, 2015). "On the other hand, Dravet's Syndrome is reported to have mutations in SCN1A, SCN2A, and SCN1B, and the mutations in both SCN1A and SCN2A lead to GEFS+." (PMID 23662118, 2013). "Another important finding was that mutations in SCN1A were evident in 33.3% of our patients clinically diagnosed as Dravet syndrome." (PMID 24665294, 2013). "The further confirmed molecular genetic screening of child clinically categorized as Dravet showed a heterozygous missense in exon 2 as p.S103G, which causes a serine to glycine substitution in N-terminus of SCN1A gene and results in Dravet syndrome." (PMID 24665294, 2013). "In patients clinically recognized as Dravet syndrome, mutations in SCN1A gene are detected in 33-100% of cases." (PMID 24665294, 2013). "Of them, nine had already been diagnosed with clinical Dravet syndrome by their treating physician and pathogenic SCN1A-mutations had been detected in eight of them." (PMID 23762420, 2013). "Postnatal day 15-21 heterozygous SCN1A-R1407X knock-in mice, expressing a human Dravet syndrome mutation, were used to investigate a possible cardiac phenotype." (PMID 24155976, 2013). "The majority of Dravet syndrome patients have denovo mutations in SCN1A, resulting in haploinsufficiency." (PMID 24155976, 2013). "Nowadays, more than 60 heterozygous pattern SCN1A mutations, which many are de novo mutations, have been detected in Dravet syndrome." (PMID 24665294, 2013).
Dravet syndrome (continued). "Based on available clinical data, we additionally diagnosed Dravet syndrome in four children, and detected pathogenic SCN1A-mutations in all four." (PMID 23762420, 2013). "Dravet syndrome is a devastating infantile-onset epilepsy syndrome with cognitive deficits and autistic traits caused by genetic alterations in SCN1A gene encoding the α-subunit of the voltage-gated sodium channel Nav1.1." (PMID 23639079, 2013). "Subsequent sequencing of the SCN1A gene (Swiss-Prot P35498) known to cause Dravet syndrome uncovered a heterozygous frameshift mutation (c.2675delA, p.N892fsX2) in the intracellular loop between DIIS4 and DIIS5." (PMID 19763161, 2009). "Six out of seven of our Dravet syndrome patients with SCN9A variants harbor either missense or splice site mutations in SCN1A while a sizable portion of published SCN1A mutations are predicted to lead to truncated proteins." (PMID 19763161, 2009). "This is based on the observation that over 50% of Dravet syndrome patients have de novo SCN1A mutations yet belong to families with a history of FS." (PMID 19763161, 2009). "In an analysis of a cohort of 109 Dravet syndrome patients, 50% of whom had SCN1A mutations, we found 8 additional SCN9A variants within the transmembrane domains and intracellular and extracellular loops of Nav1.7 in 9 patients." (PMID 19763161, 2009). "After one of these children with FS later developed Dravet syndrome (severe myoclonic epilepsy of infancy), we sequenced the SCN1A gene, a gene known to be associated with Dravet syndrome, and identified a heterozygous frameshift mutation." (PMID 19763161, 2009). "In multiple published studies, some Dravet syndrome patients inherit SCN1A mutations from asymptomatic or mildly affected parents, making multiple mutations in this syndrome a likely finding." (PMID 19763161, 2009). "Dravet syndrome (DS) is a genetically determined epileptic encephalopathy mainly caused by de novo mutations in the SCN1A gene." (PMID 19214208, 2009). "Similarly, mutations in ATP1A2 (responsible for FHM2) and SCN1A (associated with Dravet syndrome and other epileptic syndromes) disrupt potassium and sodium channel function, respectively, lowering thresholds for both CSD and epileptiform activity." (PMID 40949139, 2025). "In the specific network situation characterizing Dravet syndrome, the consequences of the sodium voltage‐gated channel alpha subunit 1 (SCN1A) genetic variants and the resulting interneuronopathy can be worsened by non‐selective modulators of voltage‐gated sodium channels." (PMID 40770908, 2025). "Professor Ingrid E. Scheffer led with 34 publications and 2,490 citations, reflecting her pivotal role in bridging clinical and genetic research—including contributions to DEE classification and the identification of SCN1A variants in Dravet syndrome, a prototypical DEE." (PMID 41476743, 2025). "The SCN1A gene, which encodes one of nine voltage-gated sodium channels essential for neurological function, is the most common pathogenic gene associated with Dravet syndrome (DS)." (PMID 41585885, 2025). "Low‐dose (5%) CO2 reliably suppresses absence, febrile, and focal seizures, while higher concentrations (e.g., 10%) may be required in certain genetic contexts, such as Dravet syndrome with Scn1a mutations." (PMID 41342230, 2025). "In general, the complete loss of expression of one SCN1A allele is expected to result in haploinsufficiency and may result in the most severe Dravet syndrome phenotype." (PMID 40903466, 2025). "Many SCN1A gene variants have been identified in Dravet syndrome, with over 2000 pathogenic variants of the SCN1A gene reported so far5, last evaluated on 26 May 20246." (PMID 40903466, 2025). "The research group of G. Colasante and V. Broccoli showed symptoms of Dravet syndrome were partially reversable in a conditional mouse model in which the KO of the Na+ channel encoding gene Scn1a could be switched off at different time points." (PMID 39895633, 2025).
Dravet syndrome (continued). "Dravet syndrome patient-iPSCs develop cardiac and neural abnormalities in ways indicating neuronal hyperexcitability and predisposition for arrhythmia are caused by SCN1A haploinsufficiency." (PMID 38766369, 2024). "Dravet syndrome usually begins with generalized clonic seizures in its infancy because of fever and progresses to various seizure types, often triggered by fever or seizure-induced heat due to mutations in the SCN1A gene that increases neuronal excitability." (PMID 38167335, 2024). "In addition, genetic testing was performed, targeting mutations in the SCN1A gene, which is associated with most Dravet syndrome cases." (PMID 38983583, 2024). "For example, in channelopathies such as Dravet syndrome (associated with a SCN1A mutation), autonomic and cardiac dysfunction has been hypothesized during paroxysmal episodes in fever." (PMID 39061411, 2024). "SCN1A haploinsufficiency is the major mechanism underlying Dravet syndrome." (PMID 38862622, 2024). "This missense sensitivity may also explain other genes enriched for missense variants despite predominantly loss-of-function effects, such as SCN1A (Dravet syndrome)." (PMID 38781976, 2024). "Significant attention has been directed towards the scn1lab gene in zebrafish, as it is the more conserved ortholog of the human SCN1A gene, and mutations in scn1lab have been consistently linked to epilepsy phenotypes in zebrafish, echoing the pathological features observed in Dravet syndrome." (PMID 39079985, 2024). "For example, when comparing an isogenic iPSC cell line acquired from a Dravet syndrome patient with a pathogenic variant in the SCN1A gene, increased expression of tyrosine hydroxylase and increased concentration of free dopamine in the culture medium in the patient's SCN1A cell line was confirmed." (PMID 38637998, 2024). "It is known that approximately 70–85 percent of patients with Dravet syndrome have a mutation in the SCN1A gene, although the clinical manifestations associated with a given mutation may result in a diverse clinical phenotype." (PMID 38339022, 2024). "While there are still little data about impairments of brain metabolism, the studies revealed ketogenic diets to be mostly effective, particularly for Dravet syndrome with identified SCN1A mutations as well as mouse and zebrafish models with SCN1A and KCNA1 mutations." (PMID 37594756, 2024). "Dravet Syndrome (DS) is a severe developmental epileptic encephalopathy with frequent intractable seizures accompanied by cognitive impairment, often caused by pathogenic variants in SCN1A encoding sodium channel NaV1.1." (PMID 38373395, 2024). "The molecular mechanism underlying Dravet Syndrome (DS) caused by variants in SCN1A remains unclear." (PMID 39258309, 2024). "Though we investigated whether the observed variant enrichment in Dravet syndrome was driven by individuals with missense SCN1A variants but were underpowered to formally report this outcome." (PMID 37006128, 2023). "Dravet Syndrome is an NDD caused by haploinsufficiency of the SCN1A voltage-gated Na2+ channel." (PMID 36792602, 2023). "However, Dravet syndrome can result not only from SCN1A mutations, but also in genes encoding the α1, β1, β2, and γ2 GABAAR subunits." (PMID 38003469, 2023). "Heterozygous loss-of-function mutations in the Nav1.1 gene (SCN1A) are responsible for the development of the vast majority of Dravet syndrome cases, a severe early onset pediatric epilepsy coincident with cognitive impairment, deterioration of motor skills, and ataxia." (PMID 38202621, 2023). "Both SCN2A and SCN1A variants are responsible for Dravet syndrome." (PMID 37152433, 2023).
Dravet syndrome (continued). "In addition to being the most common gene associated with Dravet syndrome, SCN1A is also the most common causative gene in GEFS+, despite GEFS+ having a significantly less severe clinical presentation." (PMID 37834053, 2023). "The present study aimed to determine whether generalized tonic–clonic seizures in the Scn1a+/− mouse model of Dravet syndrome are associated with either audible mouse squeaks or ultrasonic vocalizations." (PMID 36811143, 2023). "Dravet syndrome is a severe epilepsy characterized clinically by fever sensitivity, whose main genetic cause is missense, truncation, indel and microdeletion mutations of the SCN1A gene." (PMID 36761411, 2023). "The main diagnosis of children with SCN1A variants was Dravet syndrome (DS) (72.7%), whereas patients with SCN2A and SCN8A variants were mainly diagnosed with various types of epileptic encephalopathy, accounting for 85.7% (12 of 14) and 88.9% (8 of 9) respectively." (PMID 38174099, 2023). "Dravet syndrome (DS), an intractable childhood epileptic encephalopathy with a high fatality rate, is typically caused by loss-of-function mutations in one allele of SCN1A, which encodes NaV1.1, a 250-kDa voltage-gated sodium channel." (PMID 37192002, 2023). "However, surgery cannot eliminate seizures related to gene mutations or can aggravate seizures (such as SCN1A-related Dravet syndrome)." (PMID 40217282, 2023). "Variants in SCN1A are associated with a spectrum of disorders in which the seizure phenotype is variable, from simple, self-remitting febrile seizures at the mild end, to drug-resistant epilepsy in people with Dravet syndrome at the severe end." (PMID 37006128, 2023). "Interestingly, combined treatment with valproate and stiripentol is more effective in Dravet syndrome related to SCN1A mutations compared to mutations in other genes." (PMID 38003469, 2023). "To evaluate if individuals with Dravet syndrome harbour a higher burden of additional rare variants compared to the control cohorts, we performed gene-based and gene-set collapsing analyses for rare variants across 190 epilepsy-related genes, excluding SCN1A." (PMID 37006128, 2023). "A current example of using ASOs to increase protein levels by skipping a poison exon is for Dravet syndrome, an autosomal dominant disease, which is caused by variants in the SCN1A gene causing reduced expression of voltage-gated sodium channel alpha subunit Nav1.1." (PMID 36516128, 2023). "Febrile seizure due to infection or prolonged heat exposure is a common mechanism contributing to the onset and progression of Dravet syndrome (DS) symptoms, and similar hyperthermia-induced disease exacerbation is recapitulated in juvenile Scn1a-deficient mice." (PMID 37551713, 2023). "Dravet syndrome is a devastating epileptic encephalopathy caused by Scn1a gene haploinsufficiency." (PMID 35013317, 2022). "The functional researches of SCN1A variants have confirmed that loss-of-function leading to haploinsufficiency is the main effect of both Dravet syndrome and GEFS+, although for some variants, mixed loss- and gain-of-function effects and for few variants a net gain-of-function have been observed." (PMID 35571373, 2022). "Dravet Syndrome is a severe childhood pharmaco-resistant epileptic disorder mainly caused by mutations in the SCN1A gene, which encodes for the α1 subunit of the type I voltage-gated sodium channel (NaV1.1), that causes imbalance between excitation and inhibition in the brain." (PMID 34980259, 2022). "The first involves the SCN1A gene, known to be associated with several autosomal dominant epileptic disorders (e.g., Dravet syndrome–MIM: #607208–, Developmental and epileptic encephalopathy 6b–MIM: #619317–, and Generalized epilepsy with febrile seizures plus, type 2–MIM: #604403)." (PMID 36360260, 2022).
Dravet syndrome (continued). "In models of Dravet syndrome, abnormal dendritic arborization is a pathological manifestation of Scn1a−/− deletion and has been hypothesized to contribute to loss of GABAergic tone in regions of the brain most affected by Dravet syndrome." (PMID 34445144, 2021). "Moreover, it has been suggested that patients with Dravet syndrome and patients with SCN1A variants causing loss of function of the Na+ channel should avoid Na+ channel blocking anti-epileptic drugs." (PMID 34469436, 2021). "There were 4 cases of Dravet syndrome with pathogenic variants in SCN1A gene." (PMID 34816733, 2021). "In addition, the EMA and FDA have approved stiripentol and cannabidiol for the treatment of Dravet syndrome, mainly caused by variants in the SCN1A gene." (PMID 34469436, 2021). "Dravet syndrome (DS), with an underlying variant in SCN1A, was present in 70 (24%) cases." (PMID 33903184, 2021). "Donepezil might also ameliorate oxaliplatin-induced peripheral neuropathy and confer protection against induced seizures in a mouse model (Scn1a+/-) of Dravet syndrome, an encephalopathy caused by de novo loss-of-function mutations in the SCN1A gene." (PMID 32357528, 2020). "Following this study, other rare/novel SCN9A variants were reported as putative monogenic causes of disease in individuals and small families with familial febrile seizures, FS+ and GEFS+ and as a modifier of Dravet syndrome, in some cases in the presence of accompanying SCN1A pathogenic variants." (PMID 33216760, 2020). "Similarly, in a mouse model of Dravet syndrome due to Scn1a mutation, decreased Cacna1g expression results in a partial amelioration of disease phenotypes with improved survival and reduced spontaneous seizure frequency." (PMID 32878331, 2020). "Interestingly, Dravet syndrome—a genetic epilepsy associated, in most cases, with a loss-of-function de novo mutation in the SCN1A voltage-gated sodium channel subunit —is one particular form of childhood epilepsy where CBD has shown anticonvulsant activity." (PMID 32390835, 2020). "Heterozygous loss-of-function variants of SCN1A are identified in approximately 80% of patients with Dravet syndrome, which is characterized by fever-induced status epilepticus, refractory myoclonic and absence seizures, ataxia, intellectual disability and autistic features." (PMID 32899411, 2020). "Nav1.1 (SCN1A) mutation is one of the main causes of Dravet syndrome." (PMID 33198188, 2020). "Singh and colleagues presented preliminary evidence that a mutation in the SCN9A gene may act as a genetic modifier of Dravet syndrome when found in conjunction with an SCN1A mutation." (PMID 32412666, 2020). "Furthermore, we identified a previously classified SCN1A intronic Dravet syndrome-associated variant that now lies within a deeply conserved exon." (PMID 31814998, 2019). "Importantly, we recently defined a new profound SCN1A developmental and epileptic encephalopathy far more severe than Dravet syndrome that is associated with an even earlier (6–12 weeks) seizure onset." (PMID 29892053, 2019). "For instance, pathogenic SCN1A variants are identified in 80% of patients with Dravet syndrome." (PMID 29770117, 2018). "81.25% (13/16) of SCN1A mutations were de novo and 68.8% (11/16) were novel in Dravet syndrome." (PMID 30185235, 2018). "Dravet syndrome is often caused by SCN1A mutations and has a wide variation in clinical appearance." (PMID 28469861, 2017). "Interestingly, the BTBD9 variant was detected in the same patient that carried the SCN1A variant associated with Dravet syndrome." (PMID 27541642, 2016). "Dravet syndrome (DS) is one example of a severe genetic epilepsy most commonly associated with de novo mutations in a brain-specific voltage-activated sodium channel (SCN1A)." (PMID 27066534, 2016).